FN1 (fibronectin 1)
Diseases named in the same sentence as FN1 in open-access papers (continued):
Sharing a sentence is not in itself a finding about the gene and the disease.
thyroid cancer (47 papers, 2014 to 2025). "Using 20 thyroid cancer and 7 control cancer cell lines, we discovered that variants rs200077102 within FN1 and rs78588384 within CNTN5 displayed comparable low MAF in vitro as observed in the PTC blood and tumor samples." (PMID 39770638, 2024). "FN1 expression was increased in different subtypes of thyroid carcinoma; decreased FN1 levels were associated with the suppression of cell proliferation and invasion." (PMID 39769169, 2024). "Overexpression of the FN1 gene has been implicated as a significant predictor of thyroid cancer aggressiveness and has also been shown in gastrointestinal carcinoma, renal carcinoma, hepatocellular carcinoma, and head/neck cancer." (PMID 36059672, 2022). "FN1 has also been linked with cancer aggressiveness previously, both generally and in the context of thyroid cancer." (PMID 34791326, 2022). "Previous studies have demonstrated an association between FN1 expression and the invasive, migratory, and proliferative nature of thyroid cancer cell lines." (PMID 34791326, 2022). "The PROS1 and FN1 others 12 genes alternations were identified as important diagnostic biomarkers for thyroid cancer through the meta-analysis the gene expression profiling of clinical thyroid nodules." (PMID 32164602, 2020). "Also, an increase in Fibronectin 1 (Fn1) expression, associated with aggressive thyroid cancer, was observed after 7 days of BrafV637E induction, suggesting a more advanced dedifferentiated cell state in our organoid model." (PMID 37985676, 2024). "Further validation of the association between FN1 and the development of thyroid cancer may provide new targets for treating thyroid cancer." (PMID 32337286, 2020). "The correlation between FN1 expression and clinicopathological features and prognosis in thyroid cancer was previously evaluated through the analysis of the TCGA dataset." (PMID 40423510, 2025). "FN1 is highly expressed in various cancers, including gastric, colorectal, and thyroid cancers and BRCA, and is correlated to a poor prognosis." (PMID 38601538, 2024). "In thyroid cancer cells, silencing of FN1 significantly reduced proliferation, adhesion, migration, and invasion." (PMID 39770638, 2024). "’s research, FN1 was significantly upregulated in recurrent thyroid cancer and impacted cellular migration, highlighting it as a potential prognostic biomarker." (PMID 39218967, 2024). "Sanger sequencing analyses of 20 thyroid and 5 non-thyroid cancer cell lines confirmed associations with PTC, particularly for MSTA HERV-L variant rs200077102 within the FN1 gene and HERV-L MLT1A LTR variant rs78588384 within the CNTN5 gene." (PMID 39770638, 2024). "Small interfering RNA-mediated silencing of the FN1 gene has demonstrated the involvement of FN1 in the viability, adhesion, migration, and invasive properties related to other tumors as well, e.g., thyroid cancer cells." (PMID 38611032, 2024). "Some researchers found that overexpression of FN1 was an important determinant of aggressive progression of thyroid cancer." (PMID 36418670, 2023). "The expression of FN1 is a very poor prognosis marker for various cancer types, including gastric and thyroid cancers." (PMID 38248716, 2023). "In short, PLA2R1 knockdown promotes the tumorigenesis and proliferation of thyroid cancer via the FN1-mediated ITGB1/FAK axis in vivo." (PMID 37345058, 2023). "We found that, in thyroid cancer, the expressions of FN1, APOE, and CLU were statistically significant." (PMID 33521130, 2021). "Among the top 30 hub genes obtained in PPI network, the expression levels of FN1, NMU, CHRDL1, GNAI1, ITGA2, GNA14 and AVPR1A were associated with the prognosis of thyroid cancer." (PMID 32337286, 2020). "In the present study, FN1, as a hub gene with the highest correlation with thyroid cancer, was highly expressed in tumor tissues compared with the adjacent non-tumor or normal tissues." (PMID 32337286, 2020).
thyroid cancer (continued). "RNA sequence demonstrated that several long non-coding RNAs (LncRNAs) were downregulated by TRIM29 knockdown, and LncRNA CYTOR was screened as online database exhibited that CYTOR was positively co-expressed with TRIM29 and FN1 in thyroid cancer tissues." (PMID 32994394, 2020). "In previous studies, a connection has been established between the expression of TG and FN1, in which trans-acting or protein-protein interactions affect the development of thyroid cancer." (PMID 31443155, 2019). "FN1 is known to be overexpressed in aggressive thyroid cancer, and silencing of FN1 expression significantly reduced proliferation, adhesion, migration, and invasion in thyroid cancer cells." (PMID 30911020, 2019). "For thyroid cancer, FN1 upregulation acts as an important determinant of cancer aggressiveness and participates in the epithelial‐to‐mesenchymal transition." (PMID 31304688, 2019). "In recent years, several immunohistochemical markers, such as cytokeratin-19, galectin-3, HBME-1, fibronectin-1, and intracellular sodium/iodide symporter, or their combinations have been used to differentiate benign thyroid diseases from thyroid cancer." (PMID 27446209, 2016). "Eleven of 18 BRAFV600E-specific genes were previously reported as related to thyroid cancer, with 6 documented as associated with BRAF mutation (DCSTAMP, MET, FN1, DIO1, EPHA2, and ERBB3)." (PMID 26625260, 2015). "In contrast, the other professors showed that FN1 expression correlated with the prognosis and degree of immune infiltration in thyroid cancer, suggesting that FN1 expression can be used as an immune-related biomarker and therapeutic target in thyroid cancer." (PMID 36418670, 2023). "FN1 may function in thyroid cancer cells by interacting with ITGB1 and then activating the FAK signaling pathway." (PMID 37345058, 2023). "Immunohistochemical evidence showed that the increased expression of FN1 was mainly limited to the invasive front of thyroid cancer.CLU is a glycoprotein, which is involved in many physiological and pathological processes essential to carcinogenesis and tumor growth." (PMID 35359404, 2022). "Hence, we derived seven key genes related to the prognosis of thyroid cancer: FN1, NMU, CHRDL1, GNAI1, ITGA2, GNA14, AVPR1A." (PMID 32337286, 2020). "The database GEPIA also revealed a positive co-expression of TRIM29 and FN1 in thyroid cancer." (PMID 32994394, 2020). "FN1 was first reported to be overexpressed in thyroid cancer in 1988." (PMID 30414611, 2018). "Some research showed that FN1 could help distinguish benign from malignant thyroid tumors, which is consistent with our findings." (PMID 27793213, 2016). "Additionally, FN1 is commonly upregulated in aggressive forms of thyroid cancer." (PMID 31443155, 2019). "PLA2R1 competed with FN1 to bind ITGB1 to mediate extracellular matrix remodeling and thereby inhibit thyroid cancer progression." (PMID 37345058, 2023). "First, FN1, IDH2, and VDAC1 were more highly expressed in thyroid cancer tissues than in normal tissues; however, FABP4 and TG were less highly expressed in thyroid cancer tissues." (PMID 36418670, 2023). "Among differentially expressed genes, modulation of FN1, ITGα3, and MET had a significant impact on thyroid cancer cell migration." (PMID 34791326, 2022). "The Human Protein Atlas (HPA)-based Immunohistochemistry (IHC) database showed that FN1, NMU, and ITGA2 were upregulated in thyroid cancer tissues compared with normal tissues, while CHRDL1, GNAI1 and GNA14 were downregulated in thyroid cancer tissues." (PMID 32337286, 2020). "FN1, a fundamental component of the extracellular matrix, has been considered as a biomarker of PTC, and an important modulator of thyroid cancer aggressiveness." (PMID 31324198, 2019). "Survival analysis indicated that the high expression of FN1 and NMU genes significantly decreased disease-free survival of patients with thyroid carcinoma." (PMID 30872410, 2019).
thyroid cancer (continued). "Further exploration of the consistently modulated genes, particularly FN1, PIK3R1, and TGFBR1, may reveal new molecular insights and therapeutic targets for managing aggressive thyroid cancers." (PMID 40650218, 2025). "In addition, according to the results of Co-IP, FN1 expression was negatively correlated with PLA2R1 expression and positively correlated with ITGB1 expression in thyroid cancer." (PMID 37345058, 2023). "By attenuating the interaction of FN1 with ITGB1, overexpressed PLA2R1 suppresses the activation of the downstream FAK-signaling pathway, which in turn influences the malignant proliferation of thyroid cancer cells." (PMID 37345058, 2023). "Previous studies demonstrated that FN1 is a potential therapeutic target highly related to tumor invasion in PTC and medullary carcinoma, and it is also one of the markers to distinguish malignant from benign nodules in thyroid cancer." (PMID 34221185, 2021). "The bioinformatics analyses by combination of miRNA prediction databases and negative co-expression in thyroid cancer tissues were applied to explore the potential FN1 mRNA targeting miRNAs." (PMID 32994394, 2020). "In addition, survival analysis showed that the high expression of FN1 and NMU genes significantly decreased DFS of patients with thyroid carcinoma." (PMID 30872410, 2019). "The results showed that FN1 could be a potential biomarker for predicting the progression of thyroid cancer, regardless of tumor classification." (PMID 36418670, 2023). "Therefore, we hypothesized that the overexpressed PLA2R1 competes with FN1 to bind ITGB1 and inhibit the activation of the downstream FAK-signaling pathway by attenuating the interaction between FN1 and ITGB1, thereby affecting the malignant proliferation of thyroid cancer cells." (PMID 37345058, 2023).
atherosclerosis (42 papers, 2011 to 2026). A disease characterized by the build-up of fatty material and calcium deposition in the arterial wall resulting in partial or complete occlusion of the arterial lumen. "To validate sensitivity towards the known genes implicated in phenotypic switching of SMCs in atherosclerosis, we confirmed that markers of synthetic SMCs (Fn1, Col1a1, Col3a1, Col1a2, Eln, and Vcam1) were elevated in SMCTRAP-AS compared with SMCTRAP." (PMID 38289873, 2024). "The expression of atherosclerosis-associated modulation markers Lgals3, Fn1, and Serpine1 (encoding PAI1) was increased at baseline and with 2.5 μg/mL MBD-Chol in the PcntSMC–/– SMCs, but these markers did not increase in the WT SMCs until 10 μg/mL MBD-Chol." (PMID 37937642, 2023). "Aberrant FN1 expression is also associated with a multitude of diseases, including cancer, atherosclerosis, and arthritis." (PMID 35295271, 2022). "FN1 has been implicated in a number of diseases, including atherosclerosis." (PMID 28319050, 2017). "LC-MS/MS-based serum proteomic analysis of Atherosclerosis (AS) and Anaphylaxis (AP) mice identified fibronectin 1 (FN1), platelet glycoprotein Ibα chain (GP1BA), and platelet factor 4 (PF4) as candidate biomarkers." (PMID 41828395, 2026). "CELSR2, FN1, SPARCL1, APOE, LPA, APOA5, and TGFB1 exhibit causal associations with both atherosclerosis and four cardiovascular diseases, suggesting their potential as therapeutic targets for atherosclerosis." (PMID 40649979, 2025). "In the network, the maximum degree node was ocu-cirR-novel-18038 (degree=60), which is located in the FN1 gene and competes with many atherosclerosis-related mRNAs." (PMID 30187887, 2018). "Five of them (ANGPTL4, APOB, BRAP, LPA, and ZPR1), were associated with increased levels of arteriosclerosis/atherosclerosis and risk of CVD, whereas four (DUSP13, FN1, IL6R, and MMP12) were associated with reduced levels of arteriosclerosis/atherosclerosis and risk of CVD." (PMID 42133815, 2026). "Additionally, a cell population co-expressing contractile genes with key ECM genes (Col1a1, Mgp, Eln, Fn1, Col4a1, and Col8a1) and Notch3, mapped together with the fcVSMC population from the atherosclerosis dataset (I-cluster 6)." (PMID 40577585, 2025). "In the cerebral artery, the interaction between MAPK1, FABP5 (recombinant human fatty acid-binding protein-5), and FN1 (fibronectin 1) was involved in the biological processes of response to wounding, which may accelerate the process of atherosclerosis." (PMID 34306013, 2021). "In rat atherosclerosis PCR array, Abca1, Bax, Bcl2, Bcl2a1, Cd44, Fabp3, Hbegf, Lypla1, Ptgs1, Selplg, Tgfb2, Tnc, and Vegfa had reverse trend between WT and MU groups, while the trends of Bcl2l1, Bid, Birc3, Cxcl1, Fas, Fn1, Itga2, Itga5, Lif, Nfkb1, Nr1h3, Ppard, and Sod1 were consistent." (PMID 34545275, 2021). "Interestingly, a recent experimental study showed that FN1 determines the inflammatory responsiveness of endothelial cells to disturbed flow patterns, suggesting an important role of FN1 in the early stage of atherosclerosis." (PMID 28319050, 2017). "The three most promising proteins (CELSR2, FN1, and SPARCL1) were identified as potential therapeutic targets for atherosclerosis, while APOE, LPA, APOA5, TGFB1, and AGER also hold potential as drug targets for the disease." (PMID 40649979, 2025). "We identified several other important proteins whose levels inside circulating EVs were significantly higher in the CSC group than in the HCs and were related to atherosclerosis progression, such as FGC, FN1, and VWF." (PMID 34356850, 2021). "The mouse phenotypes also confirm that the modules contain attractive CAD drug target candidates, as many of the genes have a driver role for atherosclerosis (e.g. TNF and FN1) (for more details and references see69)." (PMID 29467471, 2018). "Additionally, one existing drug targeting FN1 and two drugs targeting TGFB1 have the potential for repurposing in atherosclerosis treatment." (PMID 40649979, 2025).
atherosclerosis (continued). "FN1 and TGFB1 have the potential for drug repurposing in atherosclerosis treatment." (PMID 40649979, 2025). "An unannotated disease-specific cell cluster (A-cluster 6) co-expressed contractile VSMC markers (Myh11, Acta2, and Cnn1) with several atherosclerosis-induced ECM genes (Col1a1, Mgp, Eln, Fn1, Col4a1, and Col8a1) and had reduced levels of Ly6a, Vcam1, and Tnfrsf11b compared to imVSMCs." (PMID 40577585, 2025). "The upregulation of FN1, SOX9 was observed during atherosclerosis." (PMID 36456628, 2022). "Many of the genes differentially regulated during monocyte-to-macrophage differentiation (downregulated genes include JAK2, STAT6, TLR8, and TLR2, and upregulated genes include VEGFB, TGFB1, FN1, IL-1R2, SCARB1, MSR1, and CD163) have been previously reported in the pathogenesis of atherosclerosis." (PMID 25011540, 2014). "Notably, FN1 and TGFB1 have approved drugs targeting other diseases, which may be repurposed for atherosclerosis treatment." (PMID 40649979, 2025). "The ECM genes, such as Dcn, Mgp, Fn1, and Bgn were markedly increased in EndMT+ cell, and DDC feeding further enhanced the expression of Dcn and Fn1, in line with a prior study identifying that ECs transform toward a mature fibroblast-like phenotype during atherosclerosis progression." (PMID 34095155, 2021).
colorectal cancer (41 papers, 2010 to 2025). A primary or metastatic malignant neoplasm that affects the colon or rectum. "Other studies showed that reduced DAG1 protein expression is associated with poor outcome of colorectal cancer; downregulation of FN1 decreases proliferation, migration, and invasion of colorectal cancer cells, while TNC induces EMT and proliferation." (PMID 34938324, 2021). "The enriched pathways included the Wnt signaling pathway (for somatic mutated gene DST eQTL), colorectal cancer (for somatic mutated gene FN1 eQTL) and Gap junction (for LOH mutated gene ABCA13 eQTL) with P-values 0.018, 0.012 and 0.013, respectively." (PMID 21114830, 2010). "One deleterious mutation reported in the FN1 may be related to the IBD- associated colorectal cancers." (PMID 35692981, 2022). "In line with this, FN1 has been shown to promote colorectal cancer progression by enhancing cell viability, invasion, and migration through interaction with ITGA5." (PMID 40860666, 2025). "It is noteworthy that FN1 has been determined as a promoter of malignancy in diverse types of cancer, such as breast and colorectal cancer." (PMID 38216996, 2024). "For example, L19‐TNF‐alpha and Ocriplaimin that target FN1 (cluster IV), have been employed in treating colorectal cancer." (PMID 39207047, 2024). "Knockdown of FN1 resulted in reduced cell proliferation and migration in colorectal cancer cells, suggesting FN1 as a potential therapeutic target for pterygia." (PMID 35174178, 2021). "Changes in FN1 expression level, organization or degradation are related to several types of cancer, such as lung, breast, prostate, bladder, head and neck and colorectal cancer, candidating FN1 as biomarker for diagnosis or monitoring cancer progression." (PMID 33731188, 2021). "Down-regulation of FN1 can inhibit proliferation, migration and invasion, thereby inhibiting the occurrence of colorectal cancer." (PMID 34276798, 2021). "Furthermore, the downregulation of FN1 inhibits the proliferation, migration, and invasion of colorectal cancer cells." (PMID 38601538, 2024). "Hence, the relative expression of the IL-1β, IL-2, CXCL8, and FN1 was overexpression by colorectal cancer and administration of 5-FU." (PMID 38637796, 2024). "In addition, FN1 was identified as an important regulatory factor to promote formation and development of diverse tumor cells, such as colorectal cancer and gastric cancer." (PMID 33931579, 2021). "It was suggested that FN1 could be a prognostic factor and a potential therapeutic target in colorectal cancer and could also serve as a biomarker significantly associated with OS in certain cancers, including BC." (PMID 32228629, 2020). "What is noteworthy is that, NCBI GEO gene expression database of TECs in colorectal cancer and lymphoma also verified the specific high expression of 7 out of these 12 ECM associated genes in TECs from colorectal cancer and lymphoma, i.e. SPON2, BMP-1, FN1, POSTN, THBS2, VCAN and AEBP1." (PMID 29541388, 2018). "Moreover, miR132-3p might target the FN1 in colorectal cancer." (PMID 38637796, 2024). "Furthermore, miR132-3p could target the FN1 in colorectal cancer." (PMID 38637796, 2024). "In 5 independent gastric and colorectal cancer cohorts obtained from GEO and TCGA, RNF112 was negatively correlated with FOXM1 downstream genes, including CKS1, CCNB1, SKP2, and FN1." (PMID 37288663, 2023). "FN1 interacted with binding partner ITGA5 and promoted viability, invasion, and migration in colorectal cancer through suppressing apoptosis." (PMID 36212151, 2022). "KEGG analysis indicated that FN1 was enriched in the PI3K/AKT and focal adhesion pathways, which is in agreement with previous findings that FN1 regulated colorectal cancer spread through PI3K signalling." (PMID 32228629, 2020).